IRS2 (insulin receptor substrate 2)
Diseases named in the same sentence as IRS2 in open-access papers (continued):
Sharing a sentence is not in itself a finding about the gene and the disease.
Obesity (continued). "Obesity in the domestic cat has been linked to decreased IRS-1 and IRS-2 expression levels in liver and skeletal muscle." (PMID 24312255, 2013). "Noted is the positive correlation between A2bAR expression and obesity (e.g. waist circumference), and particularly a remarkable correlation (R = 0.843; p = 6×10−11) between A2bAR and IRS-2 mRNA expression." (PMID 22848385, 2012). "IRS-1 is induced in high insulin conditions including the post-prandial state and obesity, whereas IRS-2 is increased in low insulin states such as fasting and caloric restriction." (PMID 22745692, 2012). "Our findings in subcutaneous fat from obese patients suggest that the A2bAR should be further explored as a marker of IRS-2 expression and of obesity, as well as considered as a therapeutic target." (PMID 22848385, 2012). "We also measured A2bAR and IRS-2 mRNA expression, and calculated the correlation between A2bAR mRNA expression and parameters of obesity or IRS-2 mRNA using the Spearman correlation coefficient (R)." (PMID 22848385, 2012). "Owing to the role of IRS2 in energy metabolism and lipid metabolism, drugs that target IRS2 may help alleviate obesity and related metabolic diseases." (PMID 40747301, 2025). "Previous studies have emphasized the importance of IRS2 in obesity and metabolic regulation." (PMID 41013182, 2025). "In a mouse model study, when IRS2 was knocked out, obesity and insulin sensitivity decreased." (PMID 37608331, 2023). "IRS2 is known to have an essential role in hypothalamic regulation of appetite and obesity." (PMID 34220716, 2021). "The authors showed further that in human subjects with obesity, A2B receptor expression correlated strongly with expression of the insulin receptor substrate 2, and suggested that A2B receptor agonists have potential for the treatment of type 2 diabetes and obesity." (PMID 29619754, 2018). "IRS2 expression in the hypothalamus is also important in energy homeostasis, as mice lacking IRS2 in a specific subset of hypothalamic neurons display hyperphagia, obesity and increased body length." (PMID 27514532, 2016). "To address this paradox, we proposed the hypothesis that Irs1-mediated insulin signalling is enhanced, whereas Irs2-mediated insulin signalling is impaired in the liver in type 2 diabetes and obesity." (PMID 27708333, 2016). "Thus, hyperphagia and obesity observed in IRS2-KO mice was paralleled with the impaired sensing of insulin by NG neuron." (PMID 23840624, 2013). "In addition, the IL-4/IRS2 pathway is essential for M2 activation in the steady state of VAT, whereas in obesity, hyperinsulinemia inhibits the IL-4/IRS2 pathway by reducing IRS2 expression on macrophages, which finally leads to the impairment of M2 activation." (PMID 34421909, 2021). "Thus, IRS-2/PI3K/Akt has been a target for the development of drugs used to treat obesity or T2DM." (PMID 33884100, 2021). "The results suggest that hyperphagia and obesity, disorders of the primarily central origin, observed in IRS2-KO mice and neuron-specific IRS2-KO mice, could be, at least partly, due to impaired ability of NG neuron to sense insulin and thereby convey its information to the brain in IRS2-KO mice." (PMID 23840624, 2013). "Thus, if a relative increase of IRS-1 signaling is paramount in the pathogenesis of obesity comorbidities, then a pharmacologic means of restoring IRS-2 signaling might prove to be a viable therapeutic option." (PMID 22745692, 2012). "It has been suggested that in obesity and T2DM the IRS2-mediated insulin signaling is impaired in hepatocytes." (PMID 40572705, 2025). "Western blotting confirmed that HB supplementation impacted the IRS2/PI3K/AKT signaling pathway; Conclusions: HB alleviates HFD-induced obesity and liver injury in an obese rat model possibly through the IRS2/PI3K/Akt signaling pathway." (PMID 39458511, 2024).
Obesity (continued). "They reported that adipogenic and insulin signaling genes (CEBPB, PPARG, ADIPOQ, IRS-1, IRS-2, GLUT4, among others) were downregulated in obesity." (PMID 36432612, 2022). "Previous studies have demonstrated that depletion of IRS2 and inhibition of PI3K in the hypothalamus promoted hyperphagia and obesity." (PMID 33013300, 2020). "Administration of the muscarinic agonist bethanechol increased insulin secretion and improved glucose tolerance in insulin-receptor substrate 2 (IRS2)-knockout (IRS-2−/−) mice and diet-induced obesity mice." (PMID 31700039, 2019). "Examples of genome-wide significant age-associated sites include CpG loci located in the promoter region of the obesity gene LEP, the childhood obesity gene OLFM4, the T2D gene IRS2, and the newly identified MetS gene TFAP2B." (PMID 25806089, 2015). "Meanwhile, independent of obesity, the presence of IRS2 does not only affect tumorigenesis but its detrimental effects have also been highlighted in other therapies." (PMID 35816477, 2022). "Obesity changes the secretion of adipose tissue inflammatory cytokines, which modulate insulin signaling, so we analyzed the insulin signaling gene expression including insulin receptor (IR), insulin receptor substrate 1 (IRS-1), and IRS-2 in liver tissue." (PMID 29085434, 2017). "Irs4-/y) developed severe obesity suggesting that IRS4 synergizes and complements IRS2." (PMID 28257443, 2017). "Genome-wide linkage studies of obesity and BMI have not identified IRS2 as an important locus; however, the 13q region near IRS2 showed some evidence of linkage to BMI in a recent meta-analysis." (PMID 18611262, 2008).
type 2 diabetes (60 papers, 2008 to 2026). "Studies showed that IRS2 is implicated in type 2 diabetes, and its expression is upregulated in DR mouse models." (PMID 39348384, 2024). "Differently, IRS2 expression in macrophages was downregulated by hyperinsulinemia which is often associated with type 2 diabetes." (PMID 39348384, 2024). "β cell failure in the IRS2-deletion mouse type 2 diabetes model is, in part, due to loss of CDK4 regulator cyclin D2." (PMID 37712417, 2023). "The multi-layered epigenetic network is involved in subtle dysregulation of IRS2 via IRS2 DNA methylation at CpG5, and enhanced expression of miRNA hsa-let-7e-5p in the liver has been associated with type 2 diabetes." (PMID 36295527, 2022). "In IRS2-deficient mice with consequent type 2 diabetes, some have attributed the reduced β cell mass to a failure of β cells to re-enter the cell cycle following division." (PMID 32554797, 2020). "While some studies have shown that G1057D variant of IRS-2 gene predisposes mice to type 2 diabetes." (PMID 31404179, 2019). "Studies that included individuals from Kurdish Ethnic Group (in West Iran) and Asian Indians reported association of G1057D polymorphism of IRS-2 gene with type 2 diabetes." (PMID 31404179, 2019). "Loss-of-function mouse mutants in irs2, for example, develop type II diabetes, and specific polymorphisms in human irs2 are associated with decreased or increased risk for development of type II diabetes." (PMID 25840431, 2015). "Moreover, in a large-scale epigenome-wide association study (EWAS), in blood samples, DNA methylation of the CpG site cg25924746, which is located in the shore region of the IRS2-related CpG island, was associated with type 2 diabetes." (PMID 32710190, 2020). "Another study reported IRS-2 polymorphisms as one of the genetic causes of type 2 diabetes." (PMID 31404179, 2019). "The unbalance between IRS-1 and IRS-2 caused by miR-126 may play an important role in type 2 diabetes." (PMID 26919700, 2016). "The loss of Irs-2 expression in β-cells has been linked to type 2 diabetes in humans: microarray comparison revealed that Irs-2 is significantly reduced in islets of patients with type 2 diabetes, as compared with controls." (PMID 23560040, 2013). "Type 2 diabetes (T2D) has a feature whereby polymorphisms in genes including IRS1 (Insulin Receptor Substrate 1) and IRS2, which regulate insulin signaling routes, define insulin resistance." (PMID 40430848, 2025). "We measured hepatic IRS2 expression in liver tissue of obese individuals who were stratified by type 2 diabetes, as well as liver fibrosis and steatosis status (NAS)." (PMID 32710190, 2020). "We found a significant downregulation of IRS2 expression in the liver of obese individuals with type 2 diabetes (0.84 ± 0.08-fold change; p = 0.0833; adjusted p value [pa] = 0.0417; n = 31) in comparison with non-diabetic obese participants (n = 50)." (PMID 32710190, 2020). "It had previously been shown that some species of Lactobacilli had the ability to attenuate, inter alia, type 2 diabetes through increasing the mRNA level of IRS2 in rodents." (PMID 33614758, 2020). "We aimed to investigate the relationship of type 2 diabetes with a Gly972Arg (G972R) variant of the IRS-1 gene and Gly1057Asp (G1057D) polymorphism of IRS-2 gene in the population of Punjab, Pakistan." (PMID 31404179, 2019). "The fact that NaW treatment affects glycogen metabolism in renal proximal tubules in IRS2-KO mice, similar to glycogen storage disease type 1a, turns on a red light on its potential use as a drug for type 2 diabetes treatment." (PMID 30003110, 2018). "In this study, the mechanisms controlling IRS2-dependent insulin signaling were analyzed using the db/db mouse model of type 2 diabetes and the MIN6 mouse insulinoma cell line." (PMID 28886131, 2017).
type 2 diabetes (continued). "In adipocytes isolated from obese humans with type 2 diabetes, expression of IRS-1 is reduced, followed by IRS-1–associated PI3K activity decreased, then IRS-2 becomes the main docking protein for PI3K." (PMID 27070590, 2016). "The mouse irs2 has been shown to modulate cell growth and metabolism downstream of insulin receptor signaling, and irs2−/− knockout mice develop type 2 diabetes." (PMID 25840431, 2015). "Furthermore, the expression of Irs2 was found to be significantly reduced in the livers of patients with type 2 diabetes." (PMID 40426854, 2025). "Additionally, CpG6, which is located in intron 1 of IRS2, was hypomethylated in type 2 diabetes; this site spans the sterol regulatory element binding transcription factor 1 (SREBF1) recognition motif, which likely acts as transcriptional repressor." (PMID 32710190, 2020). "Our study highlights a new multi-layered epigenetic network that could be involved in subtle dysregulation of IRS2 in the liver of individuals with type 2 diabetes." (PMID 32710190, 2020). "Because hepatic IRS2 expression is decreased in individuals with type 2 diabetes, we hypothesised that epigenetic mechanisms could play a role in this downregulation." (PMID 32710190, 2020). "Our prediction identified the m6A genes HNF1B, HNF1A, WFS1, and IRS2 as the potential disease genes, which could provide a new clue to study the role of m6A in type 2 diabetes." (PMID 30601803, 2019). "The lower of serum miR-126 in type 2 diabetic patients may cause the unbalance of IRS-1 and IRS-2 and therefore promote the pathological injury of β cells." (PMID 26919700, 2016). "Physiologically, IRS2 has been shown to play a central role in peripheral insulin signaling and pancreatic beta cell proliferation, as knockout of Irs2 in mice results in resistance to insulin and the development of type 2 diabetes." (PMID 25594065, 2014). "Interestingly, reduced expression of Irs2 has been detected in islets of patients with Type 2 diabetes." (PMID 23741292, 2013). "Male Irs2-/- mice develop fatal type 2 diabetes at 13-14 weeks." (PMID 20604929, 2010). "Thus, it is possible that mTORC1 impairs β-cell survival in type 2 diabetes both by increasing IRS2 degradation and by enhancing the stress response to glucose and fatty acids." (PMID 19305497, 2009). "Moreover, IRS2 and HK2 were associated with type II diabetes mellitus." (PMID 37958518, 2023). "DNA methylation of the IRS2 promoter-associated EWAS marker cg25924746 is increased (in a sex-dependent manner) in the liver of type 2 diabetic participants, further strengthening our hypothesis that hepatic DNA methylation of IRS2 could play a role in type 2 diabetes." (PMID 32710190, 2020). "Thus, we hypothesise that IRS2 dysregulation plays a key role in the manifestation of type 2 diabetes, as well as liver steatosis, in humans." (PMID 32710190, 2020). "As a corollary to menin-ARS2 complex repressing Irs2, a key player in regulating beta cell mass and function, the discovery of a small molecule that interferes with this binding may hold considerable promise for use in the treatment of type 2 diabetes." (PMID 25594065, 2014). "Western blot findings demonstrated that polysaccharides enhanced the protein expressions of IRS2, PI3K, and glycogen synthase and lowered that of GSK-3β in the liver of type 2 diabetic mice." (PMID 31337059, 2019). "For instance, SOCS1 degrades IRS1 and IRS2, required for insulin signaling, via the SOCS Box domain, thus, limiting its potential in type-2 diabetes." (PMID 31105556, 2019). "Although IRS2 mutations are unusual and have not been associated with human type 2 diabetes, enhanced phosphorylation on serine/threonine residues, many of which negatively regulate IRS2 function, may affect the proper IRS2 downstream signals, which in turn would affect NaW renal effects." (PMID 30003110, 2018).
type 2 diabetes (continued). "In contrast, no bladder enlargement was observed in the other type 2 diabetes models (two out of three studies with fructose-fed rats, IRS2 knock-out mice, all three studies with HFD in mice)." (PMID 36003651, 2022). "IRS2 expression was found to be decreased in the liver of obese individuals with type 2 diabetes (n = 31) vs obese individuals without type 2 diabetes (n = 50) (0.84 ± 0.08-fold change; p = 0.0833; pa = 0.0417)." (PMID 32710190, 2020). "As far as we know, two previous studies in humans, with small sample size (n = 39–40), examined protein or gene expression of the IGF1, IGF2, IGFBP3, INSR, IGF1R and downstream targets IRS1, IRS2 and mTOR in women with or without type 2 diabetes." (PMID 29486734, 2018). "Given their central role in the insulin signalling pathway, it is not surprising that male mice lacking Irs1 or Irs2 present with elevated blood glucose or type 2 diabetes, respectively." (PMID 27514532, 2016). "While the IR isoform A to B as well as the IRS-1 to IRS-2 ratios were not different in patients with type 2 diabetes, we found IGF-1 receptor to be reduced in this patient group." (PMID 23251408, 2012). "IRS1 null mice have much reduced growth (30-60% of control), whereas IRS2 null mice have almost normal growth (about 90% of control), but develop type 2 diabetes, therefore IRS1 is thought to be downstream of the IGF1 receptor, and IRS2 downstream of the insulin receptor." (PMID 21798082, 2011). "In contrast, mice lacking Irs2 develop type 2 diabetes, with Irs2-/- male mice displaying both insulin resistance and β-cell failure at an early age." (PMID 20604929, 2010). "The impact analysis also revealed the enrichment of the “Type II diabetes mellitus” pathway resulting from the upregulation of MAPK10 and IRS2 and the downregulation of CACNA1A and SOCS2, a signature that may upregulate the insulin receptor (INSR), PI3K, and insulin resistance." (PMID 36835058, 2023). "Here, we show a multi-layered epigenetic mechanism that could be involved in downregulation of IRS2 expression in the liver of obese individuals with type 2 diabetes, as compared with obese individuals without type 2 diabetes." (PMID 32710190, 2020). "Since IRS2 reportedly plays a very important role in pancreatic β cell proliferation, the identification of the HDAC isoforms involved in these mechanisms may be a valuable approach for the treatment of type 2 diabetes." (PMID 28886131, 2017).
breast carcinoma (49 papers, 2006 to 2025). "In contrast, IRS2 expression is elevated in more aggressive subtypes such as Basal/Triple Negative Breast Cancer (TNBC), and the membrane-localized expression of IRS2 is associated with reduced overall survival of breast cancer patients." (PMID 39305958, 2024). "Membrane staining of IRS-2 is associated with decreased overall survival in breast cancer patients, in particular in patients with progesterone receptor (PR) negative tumors." (PMID 36556357, 2022). "IRS2 expression is higher in aggressive, metastatic human breast carcinoma cell lines, and mammary tumor cells that are deficient for IRS2 expression are significantly more sensitive to apoptotic stimuli, such as serum deprivation." (PMID 26755644, 2016). "Several studies have evaluated the association between IRS2 rs1805097 (G>A) polymorphisms and the risk of colorectal and breast cancer." (PMID 24497996, 2014). "Irs-2-deficient PyV-MT-derived mammary tumor cells are significantly more sensitive to serum deprivation-induced apoptosis than wildtype tumor cells, and Irs-2-/- tumors also have a higher in situ level of apoptosis." (PMID 19534786, 2009). "Three of the 11 tagging SNPs for IRS2 were associated with breast cancer (rs4773082, P = 0.007; rs2289046, P = 0.016; and rs754204, P = 0.03)." (PMID 18611262, 2008). "Three SNPs in IRS2 were associated with breast cancer and were also found to be in LD (rs4773082, rs2289046, and rs754204)." (PMID 18611262, 2008). "The first study sequenced coding regions to identify variants of interest, and then examined two IRS2 SNPs (rs4773092 and rs1805097) in a familial breast cancer study." (PMID 18611262, 2008). "Data available from the Cancer Genetic Markers of Susceptibility initiative indicates that one SNP in IRS2 is marginally associated with breast cancer (rs12584136, P = 0.051)." (PMID 18611262, 2008). "Among the cases, the G allele for IRS2 rs2289046, which was protective for breast cancer, also was associated with less weight gain in adulthood compared to the A allele (P = 0.016)." (PMID 18611262, 2008). "A recent study established a sugar metabolism-related prognostic model that included IRS2 gene for breast cancer, which could distinguish low-risk patients who were more sensitive to chemotherapy." (PMID 38750402, 2024). "Mammary tumor cells deficient for IRS2 expression are more sensitive to apoptotic stimuli." (PMID 26755644, 2016). "Although reported studies have focused on the association between the IRS2 rs1805097(G>A) polymorphism and the risk of colorectal and breast cancer in diverse populations, the results remain inconclusive, partially due to the relatively small sample size in each of the published studies." (PMID 24497996, 2014). "Mammary tumor metastasis is significantly diminished in PyV-MT:Irs-2-/- mice, and Irs-1 deficient tumors that express elevated levels of active (i.e. tyrosine phosphorylated) Irs-2 have enhanced metastatic rates." (PMID 19534786, 2009). "Our results suggest that common variation in HSD11B1 and IRS2 may be associated with breast cancer among postmenopausal white women." (PMID 18611262, 2008). "Our results suggest that common variation in HSD11B1 and IRS2 may be associated with breast cancer among postmenopausal women." (PMID 18611262, 2008). "Furthermore, we do not think that the relationship between IRS2 and weight change explains the association between IRS2 SNPs and breast cancer." (PMID 18611262, 2008). "Although these data suggest that HSD11B1 and IRS2 may be associated with risk for breast cancer, it is also possible that these findings are due to chance." (PMID 18611262, 2008). "Three SNPs in IRS2 were also associated with breast cancer (rs4773082, rs2289046, and rs754204)." (PMID 18611262, 2008).